TRBV16 (T cell receptor beta variable 16)
Description:
V region of the variable domain of T cell receptor (TR) beta chain that participates in the antigen recognition. Alpha-beta T cell receptors are antigen specific receptors which are essential to the immune response and are present on the cell surface of T lymphocytes. Recognize peptide-major histocompatibility (MH) (pMH) complexes that are displayed by antigen presenting cells (APC), a prerequisite for efficient T cell adaptive immunity against pathogens. Binding of alpha-beta TR to pMH complex initiates TR-CD3 clustering on the cell surface and intracellular activation of LCK that phosphorylates the ITAM motifs of CD3G, CD3D, CD3E and CD247 enabling the recruitment of ZAP70. In turn ZAP70 phosphorylates LAT, which recruits numerous signaling molecules to form the LAT signalosome. The LAT signalosome propagates signal branching to three major signaling pathways, the calcium, the mitogen-activated protein kinase (MAPK) kinase and the nuclear factor NF-kappa-B (NF-kB) pathways, leading to the mobilization of transcription factors that are critical for gene expression and essential for T cell growth and differentiation. The T cell repertoire is generated in the thymus, by V-(D)-J rearrangement. This repertoire is then shaped by intrathymic selection events to generate a peripheral T cell pool of self-MH restricted, non-autoaggressive T cells. Post-thymic interaction of alpha-beta TR with the pMH complexes shapes TR structural and functional avidity.
Synonyms: TCRBV16S1; TCRBV25S1A2PT; BV25S1J1.2; TCRB; TCRBV25S1
Gene: T-cell receptor variable (V) gene on chromosome 7 (142,598,016 to 142,598,469, forward strand). Ensembl gene ENSG00000275243.
Subcellular location: Cell membrane
Gene Ontology:
Biological process: cell surface receptor signaling pathway
Cellular component: plasma membrane
Homologues: Orthologues: chimpanzee TRBV16 (80% identical), macaque TRBV16 (76% identical), dog TRBV16 (59% identical). Paralogues in human: TRBV23-1 (54% identical), TRBV18 (49% identical), TRBV11-2 (44% identical), TRBV12-4 (43% identical), TRBV14 (43% identical), TRBV17 (43% identical), TRBV12-3 (42% identical), TRBV2 (42% identical), TRBV7-2 (42% identical), TRBV12-5 (41% identical), TRBV7-3 (41% identical), TRBV11-1 (40% identical), and 39 more.
Diseases named in the same sentence as TRBV16 in open-access papers:
TRBV16 is named in the same sentence as 3 diseases in open-access papers, as found by Europe PMC text mining. Sharing a sentence is not in itself a finding about the gene and the disease. The quoted sentences say what the papers report.
Sjögren's syndrome (1 paper, 2025). "For the β chain, many V/J genes, which were highly expressed in cachexic HCC mice, were associated with type I diabetes, such as Trbv1 [S18,19], Trbv13‐2 [S19], Trbj2‐7 [S19,20] and with Sjögren's syndrome, such as Trbv3 [S21], Trbv16 [S22] and Trbj2‐2 [S22]." (PMID 40665793, 2025).
TRBV16 also shares sentences with these, for which no sentence is quoted: cancer (1 paper); type I diabetes (1).